EREG (epiregulin)
Diseases named in the same sentence as EREG in open-access papers (continued):
Sharing a sentence is not in itself a finding about the gene and the disease.
cancer (continued). "Together, these observations suggest EREG has a critical role in cancer development and progression." (PMID 38334792, 2024). "Multiple lines of evidence have indicated the prognostic significance of EREG expression for many human cancers, including NSCLC." (PMID 38398101, 2024). "In vitro experiments demonstrated that EREG knockdown undermined proliferation and promoted apoptosis in cancer cells." (PMID 37020674, 2023). "EREG, one of the ligands of EGFR, has a low expression in most normal tissues; however, in cancer, EREG up-regulates and activates EGFR." (PMID 37670265, 2023). "Elevated levels of EREG appear to be a potential predictive biomarker of anti-EGFR therapies in several cancer types including HNSCC." (PMID 36899869, 2023). "Recent studies have demonstrated that epiregulin (EREG) is upregulated in various cancer types, which contributes to cancer progression by triggering the EGFR signaling pathway." (PMID 37020674, 2023). "Conversely, siRNA-mediated downregulation of Xkr8 in colorectal Caco-2 cancer cells led to decreased PS externalization upon induction of apoptosis, which was accompanied by reduced shedding of endogenously expressed EREG and reduced cell survival." (PMID 37623781, 2023). "The EREG/EGFR pathway is known to play a role in cancer pathogenesis by regulating cell differentiation and growth." (PMID 35954313, 2022). "In cancer clinics, upregulated EREG expression predicts a poor prognosis, but potentially benefits from therapies involving anti-EGFR agents such as panitumumab." (PMID 36202915, 2022). "We found the viability of cancer cells substantially increased upon exposure to damaged stromal cell-derived CM, although counteracted by ~30% upon EREG knockdown or AG-1478 treatment." (PMID 36202915, 2022). "Although there is a limited number of literatures correlating MARCHF4 and cancer progression, our study suggest that cancer cell resistance driven by stromal cell-derived EREG, is at least partially mediated by MARCHF4 upregulated in recipient cancer cells." (PMID 36202915, 2022). "Although implications of EREG in cancer progression have been extensively investigated, only recently that mechanisms inherently correlated with its distinct functions were revealed." (PMID 36202915, 2022). "In HNSCC, EGF family ligand expression, including EREG, associates with better responses to the EGFR inhibitor cetuximab, reflecting the increased dependence on EGFR signaling in these cancers." (PMID 36506869, 2022). "Beyond genomic/epigenetic alterations of oncogenes and/or tumor suppressors, the epidermal growth factor receptor (EGFR) ligand EREG can function as a bona fide biomarker of therapeutic sensitivity for many EGFR-driven carcinomas." (PMID 36202915, 2022). "EREG expression was increased in CRC cells and was associated with cancer stem cell (CSC) characteristics." (PMID 34884633, 2021). "Elevated EREG expression levels appear to be a potential predictive biomarker of anti-EGFR therapies in several cancer types." (PMID 34884633, 2021). "In this review, we describe the signaling action of EREG, which plays a key role in cancer progression." (PMID 34884633, 2021). "Clinicopathological and in vitro studies have revealed that EREG expression has prognostic importance in several human cancers." (PMID 34884633, 2021). "We further screened the activated ligand-receptor pairs between ductal cells and these two stroma-cell types and defined several cancer-associated pairs, such as EGFR/TGFB1, ANXA1/FPR3, EREG/EGFR, and ICAM1/AREG." (PMID 34326696, 2021). "In our study, we found that EREG was remarkably upregulated in the HNSCC cancer cell line HN4 compared with HOK cells, as determined by microarray analysis." (PMID 32929368, 2020). "Epiregulin, meanwhile, appears to contribute to the progression of several different human cancers, including bladder, stomach, colon, breast, and other cancers." (PMID 31159449, 2019).
cancer (continued). "A high-level expression of EREG mRNA has been reported in several human cancer cell lines, which has established EREG also as an important regulator of cancer growth and metastasis." (PMID 29748481, 2018). "HepaRG, compared to RPTEC/TERT1 cells also highly express Epiregulin (EREG) and several genes associated with cancer, many belonging to the GAGE family (GAGE − 1, − 2, − 3, − 4 and − 12)." (PMID 30008028, 2018). "EGFR ligands implicated in human cancers, include EGF, EREG, amphiregulin (AREG), heparin-bound EGF (HB-EGF) and transforming growth factor alpha (TGFα)." (PMID 26958807, 2016). "Increased expression of Epiregulin has been shown to be a biomarker for several cancers Axl belongs to the TAM (Tyro-3, Axl and Mer) family of receptor tyrosine kinases." (PMID 26036314, 2015). "Similar findings for EREG high vs. low were seen when we examined complex cancer genotypes: a) KRAS+BRAF, both wild type vs. any mutant, b) KRAS+BRAF+PIK3CA+NRAS, all wild type vs. any mutant." (PMID 23374602, 2013). "Epiregulin (EREG) is a member of the epidermal growth factor family and is used as a marker of several cancers." (PMID 20126548, 2010). "Other studies have found that EREG is generally upregulated in cancer which may result from CGI hypomethylation." (PMID 40753397, 2025). "Similarly, overexpressed EREG in NSCLC contributes to cancer cell proliferation and drug resistance." (PMID 39858622, 2025). "Activation of EREG signaling is central to cancer cell proliferation, metastasis, and angiogenesis." (PMID 38250159, 2024). "Considering that bile acids can activate the transcriptional activity of FXR after the action of FXR, we hypothesized that FXR may inhibit the transcription of EREG and then play the role of cancer inhibition." (PMID 39834394, 2024). "Thus, EREG overexpression appears to be responsible for the resistance to SHP2 inhibitors in cancer cells." (PMID 38398101, 2024). "The oncogenic functions of EREG have been reported for various human cancers." (PMID 38398101, 2024). "As LGR5 is an important intestinal and cancer stem cell marker, this suggests EREG may be involved in cancer stemness." (PMID 40727266, 2024). "When combined, these findings suggest that targeting the EREG/EGFR pathways could be a strategy for cancer therapy, especially when overcoming therapeutic resistance." (PMID 38398101, 2024). "The dysregulation of EREG may contribute to the progression of various cancers including HNSCC and may be a putative mechanism of resistance to EGFR-targeted therapies." (PMID 36899869, 2023). "In particular, EREG promotes cancer progression in various human tissues." (PMID 35865633, 2022). "But it remains unclear whether EREG also regulates cancer stem cells in NSCLC and promotes chemoresistance." (PMID 35551652, 2022). "Although PSC27-BLEO CM enhanced viability of PC3 exposed to MIT at 0.1–1.0 μM, a range of dose approaching its serum concentrations in clinical settings, EREG-neutralization markedly offset cancer resistance in a similar way as EREG mAb was combined with cetuximab." (PMID 36202915, 2022). "EREG enhances glycolysis through activating EGFR signaling and its downstream glycolytic genes in tamoxifen-resistant BCa cells, whereby EREG is a direct target of miR-186-3p, downregulation of which by tamoxifen causes EREG upregulation in these cancer cells." (PMID 36202915, 2022). "The expression of EREG is upregulated in multiple cancer types." (PMID 36202915, 2022). "Inhibition of ErbB receptor or knocking-down EREG suppressed ERK signaling, decreased expression of stemness-associated genes and finally affected the stemness of resistant cancer cells, which could re-sensitize the resistant cancer cells to chemo-drugs." (PMID 35551652, 2022). "Therefore, determining the most favorable outcomes of combined therapies, including targeting EGFR, EREG, and other driver oncogenic genes in a subpopulation of patients with cancer is crucial." (PMID 34884633, 2021).
cancer (continued). "Furthermore, FLT1 of LUSC, ITGB1 of DLBC, MDM4, and CDKN1A of ACC, MAPK1, and ERBB3 of UCEC, FGFR1 of ESCA, and EREG and BCL2L1 of COAD have been strongly associated with patient survival in their respective cancers." (PMID 34079798, 2021). "The EREG/EGFR pathway may be a potential target and may be combined with other driver mutation targets to combat specific cancers." (PMID 34884633, 2021). "Collectively, the findings suggest that studies should examine whether the blockade of the oncogenic mutations of RAS, BRAF, or PI3K in certain types of cancer, such as CRC, restore EREG expression that mediates the activation of EGFR downstream signaling." (PMID 34884633, 2021). "We assumed that EGFR ligands, especially AREG and EREG, which are frequently co-expressed in carcinomas, might offer similar treatment opportunities." (PMID 33941851, 2021). "Although EREG upregulation has been found in many cancers, the molecular mechanism by which EREG promotes cancer progression in most cancers remains unclear." (PMID 32929368, 2020). "The upregulation of EREG has been found in several cancers and TSC patients." (PMID 33679864, 2020). "On the other hand, wound-healing assays, transwell assays and 3D invasion models demonstrated that altered EREG expression in fibroblasts significantly influences their supportive role in cancer cell migration and invasion, with more significant effects on invasion." (PMID 31234944, 2019). "Besides genes expressed in common with hESCs, cancer cells expressed Epiregulin (EREG) and Amphiregulin (AREG) of the EGF-receptor (EGFR) pathway, generally associated with progressed cancer." (PMID 31758153, 2019). "Although classically thought of as epithelial specific molecules that regulate EGFR signaling via an autocrine loop, production of EREG and AREG has been detected in stromal cells including normal and cancer associated fibroblasts and various immune cell populations." (PMID 30412601, 2018). "In contrast, this pathway might be redundant or irrelevant, perhaps due to a low level of activation by AREG and EREG, in cancer cells, thus rendering the blockade of EGFR by cetuximab ineffective." (PMID 27344184, 2016). "Our results imply that SPHK1 may be the central controller of amplification loops of EGF, AREG and EREG-EGFR interactions that can contribute to cancer progression." (PMID 21936950, 2011). "The lnc021545-miR-330-3p-EREG axis may act as a pivotal role in BC and even in other cancers." (PMID 37048561, 2023). "Notably, the EREG IHC score was significantly higher in cancer tissues than in normal tissues." (PMID 32929368, 2020). "In addition to the mutational status of KRAS, the epidermal growth factor receptor (EGFR) ligands amphiregulin (AREG) and epiregulin (EREG) might function as bona fide biomarkers of cetuximab (Ctx) sensitivity for most EGFR-driven carcinomas." (PMID 22491422, 2012). "EREG is highly expressed in various cancers, primarily activating the EGFR signaling pathway and promoting cancer progression." (PMID 39883700, 2025). "Accumulating evidence has demonstrated the oncogenic roles of EREG, MAFG and GAS6 in various cancers." (PMID 40819060, 2025). "EREG serves as a ligand of the epidermal growth factor receptor (EGFR) and its deregulation in different types of cancer leads to activation of EGFR signaling pathways and tumorigenesis." (PMID 38016355, 2024). "Therapeutic targeting of EREG and AREG has been studied in the context of several different EREG and/or AREG-expressing cancer types." (PMID 40727266, 2024). "i3 cancers showed higher expression of downstream MAPK components (DUSP4 and ETV5) and i2 cancers had overexpression of EGFR ligands, AREG and EREG." (PMID 35773407, 2022).
cancer (continued). "In this study, we explored the possibility of controlling cancer resistance by targeting one of the major SASP factors, EREG, which acts as a critical player in driving acquired resistance, with EREG emerging as the SASP-related targetable molecule." (PMID 36202915, 2022). "Subsequently, we analyzed the associations between EREG gene expression and DNA CNV, methylation, and ATAC-Seq using the pan-cancer atlas and found that ATAC-Seq peak intensity of EREG was a significant factor affecting prognosis." (PMID 35862975, 2022). "The expression of TNFAIP3 was higher in immune cells, especially in epithelial carcinoma, macrophages, and CD8+ T‐cells (left), while TGFBI, IFI30, SPP1, and EREG were expressed more highly in macrophages than other cells." (PMID 35634956, 2022). "Elevated EREG in various cancers mainly activates EGFR signaling pathways and promotes cancer progression." (PMID 34884633, 2021). "Combining NPG with HO-1 inhibitor demonstrated down-regulation of genes involved in cancer cell invasion and proliferation (EGR1, CXCL2, AREG, CXCL3, EREG, CD3e, CD3g, CD74, and B2M) as compared to NPG or to control animals." (PMID 34066839, 2021). "The activated EREG/EGFR pathway regulates various cellular functions, including cancer cell proliferation, survival, metastasis, and angiogenesis, thereby conferring malignant tumor phenotypes." (PMID 34884633, 2021). "By analysis of the overall survival based on EREG mRNA expression, we also found that patients with high EREG levels had a significantly shorter median overall survival than patients with low EREG levels in both HNSCC and other cancer types." (PMID 32929368, 2020). "In fact, such NOX2-dependent mechanisms are likely responsible for increased EGFR cysteine oxidation in cancer cell lines under basal conditions, due to constitutive activation of EGFR ligands such as EREG." (PMID 30890751, 2019). "Levels of MFNG in this subgroup of tumors also determined the transcriptional status of several Notch target genes such as NKD1, DLX3, EREG, EPHA4, or IL7R, known to be relevant for cancer progression." (PMID 30065304, 2018). "AREG/EREG overexpression and activation of the EGF pathway is a feature of CIN-positive CRCs, especially for carcinomas of the distal colon." (PMID 30563495, 2018). "Gene expression analysis by microarray demonstrated that MDR1A deficiency shaped the inflammatory response towards an anti-tumorigenic microenvironment by downregulating genes known to be important mediators of cancer progression (PTGS2 (COX2), EREG, IL-11)." (PMID 28686677, 2017). "In this respect, human cancer cells, which exhibit mesenchymal-like characteristics, express lower levels of EGF ligands, such as amphiregulin and epiregulin." (PMID 21750552, 2011). "Finally, we will conclude with recent progress made towards therapeutically targeting EREG and AREG in cancer with novel mAbs and ADCs." (PMID 40727266, 2024). "In inverse co-culture at both time points and standard co-culture at 72 h 26 genes were mutually expressed, among them genes of the KEGG pathway Proteoglycans in cancer, like Fibronectin 1 (FN1), Hepatocyte Growth Factor (HGF), Epiregulin (EREG) and Tissue Inhibitor of Metalloproteinases 1 (TIMP1)." (PMID 39098880, 2024). "Indeed, it has been observed that in vitro cancer cell lines as well as patients with high expression of EGFR ligands, such as amphiregulin (AREG) and epiregulin (EREG), benefit more from Cetuximab therapy." (PMID 39000238, 2024). "Additionally, we review recent advances towards therapeutic targeting of EREG and AREG in cancer through the development and use of EREG- and AREG-targeted monoclonal antibodies (mAbs) as well as antibody-drug conjugates (ADCs)." (PMID 40727266, 2024).
cancer (continued). "The data suggest development of an in vivo SASP, the index of which can be measured by quantifying concurrently expressed soluble factors, including but may be not limited to EREG and CXCL8, in the peripheral flood of post-treatment cancer patients." (PMID 36202915, 2022). "We next interrogated whether EREG, a soluble factor in the full SASP spectrum of stromal cells, plays a major role in shaping advanced malignancies of cancer cells." (PMID 36202915, 2022). "Importantly, EREG enhanced the resistance of PCa cells to MIT, a DNA-targeting chemotherapeutic drug administered to cancer patients including those developing PCa." (PMID 36202915, 2022). "Epiregulin (EREG) is a member of the epidermal growth factor family that has a similar function with EGF, which binds to the ErbB receptors to regulate the proliferation and anti-apoptosis of cancer cells." (PMID 35551652, 2022). "Moreover, treatment of SCC-25 cells with Gef and its combination with DMU-214 resulted in a down-regulated mRNA level of EREG, which as a ligand of EGFR is known to contribute to the activation of the receptor and, therefore, cancer cells proliferation." (PMID 34201116, 2021). "In summary, our results suggest that POLR1D may act as a potential driver gene in the 13q12.2 amplification and may affect cancer progression by increasing the expression of VEGFA and EREG." (PMID 32087735, 2020). "Epiregulin (EREG) considered as a hub gene in squamous cervical carcinoma and other gynecological tumors has been reported to undergo silencing in certain types of carcinoma." (PMID 32899940, 2020). "The results demonstrated that EREG expression was also significantly higher in fibroblasts from the cancer stroma (CAFs) than in fibroblasts from the stroma around normal mucosa (NFs)." (PMID 31234944, 2019). "We have shown that AREG and EREG are required for HGF-mediated migration and invasion in response to signaling from integrin α6β4, further demonstrating their importance to invasive properties of cancer cells." (PMID 28733611, 2017). "Epiregulin (EREG), the cell-membrane-expressed ligand of epidermal growth factor receptor, is expressed and integrated into the plasma membrane at relatively high levels in a variety of human cancers, including colorectal and breast cancer." (PMID 28333127, 2017). "EREG is an intratumoral marker for advanced NCSLC and is upregulated in cancer cell lines." (PMID 19925653, 2009). "This could help block the activity of EGFR ligands implicated in cancer and inflammation (e.g., AREG, EREG,) without affecting the function of TGFα in protection of the skin and intestinal barrier." (PMID 36361585, 2022). "Such a characteristic expression pattern was subsequently confirmed in several cell lines of human lung origin, including a stromal line HFL1 and several carcinoma cell lines regardless of malignancy, suggesting an organ- or tissue type-independent nature of EREG induction." (PMID 36202915, 2022). "EGFR is overepressed in many cancer types and activated by a variate of ligands, including besides EGF also the transforming growth factor-alpha (TGFA), heparin-binding EGF-like growth factor (HBEGF), betacellulin (BTC), amphiregulin (AREG) and epiregulin (EREG) and epigen (EPGN)." (PMID 32119655, 2020). "Furthermore, the TMAs contain multiple cell types, some of which may not change their expression or organization of EREG in cancer (e.g., lymphocyte, enterocyte, etc.), and which could not be identified from the dSTORM data." (PMID 41395524, 2025). "Notably, the expression of EREG in stromal cells is upregulated and activates several downstream signaling pathways, including the MAPK AKT/mTOR and JAK/STAT pathways, in cancer cells by paracrine signaling, promoting their malignant phenotype and accelerating the progression of cancer." (PMID 37077811, 2023).